SNORD18A (small nucleolar RNA, C/D box 18A)
Synonyms: U18A
Gene: Small nucleolar RNA gene on chromosome 15 (66,503,243 to 66,503,314, reverse strand). Ensembl gene ENSG00000200623.
Gene Ontology:
Biological process: RNA processing
Cellular component: nucleolus
Homologues: Orthologues: chimpanzee SNORD18 (100% identical), macaque SNORD18 (100% identical), guinea pig SNORD18A (93% identical), dog SNORD18 (92% identical), pig SNORD18 (86% identical), mouse Gm23344 (74% identical), zebrafish SNORD18 (74% identical), rat LOC120094440 (72% identical), tropical clawed frog SNORD18 (71% identical). Paralogues in human: SNORD18B (75% identical), SNORD18C (75% identical), SNORD18 (72% identical), SNORD18 (69% identical).